KLF5 (KLF transcription factor 5)
Diseases named in the same sentence as KLF5 in open-access papers (continued):
Sharing a sentence is not in itself a finding about the gene and the disease.
ovarian carcinoma (continued). "For instance, KLF5 has been reported to strengthen drug resistance in ovarian cancer cells by inducing survivin gene expression." (PMID 29898734, 2018). "Nonetheless, the majority of these genes are common to all subtypes of ovarian cancer, and several have been previously implicated in its pathogenesis, including TACSTD1 (Ep-CAM), CDH1 (E-cadherin), KLF5 (Kruppel-like factor 5) and ERB-B3." (PMID 16508639, 2006). "The findings suggest that downregulation of KLF5 can enhance the susceptibility of PARPi-resistant ovarian cancer cells to PARP inhibitors, while upregulation of KLF5 can promote resistance of PARPi-sensitive ovarian cancer cells to PARP inhibitors." (PMID 40307891, 2025). "Furthermore, overexpression of KLF5 can promote the progression of ovarian cancer and PARPi resistance, which is consistent with Wu’s findings." (PMID 40307891, 2025). "Similarly, SEs-driven KLF5 is a key regulatory factor in ovarian cancer progression and PARPi resistance; offering potential therapeutic strategies for these patients with PARPi resistance and high KLF5 are identified." (PMID 40606603, 2025). "IHC evaluated KLF5 expression in ovarian cancer tissue samples." (PMID 40307891, 2025). "Conversely, the diminished stemness of ovarian cancer resulting from KLF5 knockdown could be rescued following Vimentin overexpression." (PMID 40307891, 2025). "Flow cytometry and western blot analysis suggested the enhanced stemness of ovarian cancer induced by KLF5 overexpression could be rescued following Vimentin knockdown." (PMID 40307891, 2025). "We then evaluated whether pharmacological inhibition of KLF5 would restore the antitumor effect of olaparib on PARPi-resistant ovarian cancer cells." (PMID 40307891, 2025). "Additionally, the percentage of ALDH positive cells in ovarian cancer cells, as measured by flow cytometry, was significantly reduced after KLF5 knock down." (PMID 40307891, 2025). "Additionally, the team led by Wu was the first to discover that KLF5 can promote resistance to PARPi in ovarian cancer." (PMID 40307891, 2025). "As a selective inhibitor of KLF5, ML264 exhibits potent antitumor activity in multiple preclinical models including colorectal and ovarian cancers, and possesses favorable pharmacokinetic properties with promising safety for KLF5-targeted therapeutic strategies." (PMID 40307891, 2025). "Klf5 (also known as BTEB2 and IKLF), a member of the Kruppel-like family of transcription factors, has been implicated as an oncogene and therapeutic target in a number of cancers, including breast, colon, bladder, lung, stomach, and ovarian cancer." (PMID 33413440, 2021). "Findings come mostly from experimental studies suggesting that KLF2, KLF4, KLF6 and KLF11 act as tumour suppressors in ovarian cancer while KLF5, KLF8 and KLF9 might have a potential role in disease development and progression." (PMID 33250051, 2020). "Additionally, KLF5 has also been reported to increase drug resistance in ovarian cancer cells by inducing survivin gene expression." (PMID 28030791, 2017). "As anticipated, Western blot results demonstrated that KLF5 expression was higher in ovarian cancer tissues compared to normal fallopian tube tissues and high KLF5 expression levels demonstrated correlations with both poorer overall survival and progression-free survival in ovarian cancer patients." (PMID 40307891, 2025). "Looking at KLF5, to the best of our knowledge, the only data available refer to in vitro experiments on SKOV3 cells and showed a role for KLF5 in driving stemness and drug resistance in ovarian cancer." (PMID 33250051, 2020). "Recent studies have demonstrated that KLF5 forms a transcriptional complex with EHF and ELF3, remodeling RAD51 transcription to enhance the homologous recombination repair (HRR) pathway in ovarian cancer cells, thereby promoting ovarian cancer progression and PARPi resistance." (PMID 40307891, 2025).
ovarian carcinoma (continued). "For example, FABP4 enhances mitochondrial β-oxidation to reduce cisplatin-induced apoptosis in ovarian cancer, while FABP5 promotes chemoresistance in hepatocellular carcinoma through the HIF-1α pathway, and FABP6 enhances CRC resistance to oxaliplatin through KLF5-dependent transcription." (PMID 40717587, 2025). "Results of bioinformatic analysis on KLF2 and KLF5 were actually not in line with previous literature data indicating that KLF2 may act as tumor suppressor in ovarian cancer, while KLF5 may behave as an oncogene." (PMID 33250051, 2020). "Interestingly, a recent study showed that KLF5 forms a transcriptional complex with EHF and ELF3 and binds to the promoter region of RAD51 to enhance its transcription, strengthening the homologous recombination repair pathway and consequently inducing chemoresistance in ovarian cancer cells." (PMID 39865088, 2025).
cervical carcinoma (14 papers, 2017 to 2025). A carcinoma arising from either the exocervical squamous epithelium or the endocervical glandular epithelium. "MiR-145-5p can also suppress the proliferative, migratory and invasive rates of cervical carcinoma cells through targeting KLF5." (PMID 39039505, 2024). "KLF5 has an oncogenic role in certain types of cancer, including pancreatic, colorectal, breast, and cervical cancer." (PMID 35836107, 2022). "Our results demonstrate that KLF5 and TNFRSF11a promote cervical cancer cell proliferation, migration and invasiveness." (PMID 29146991, 2017). "Besides, we also found the correlation between Eppk1 and KLF5 in cervical cancer using the TCGA database (R = 0.18, P < 0.01)." (PMID 33827480, 2021). "Nonetheless, it is noteworthy that miR-145-5p represses KLF5 in cancer cell lines and bronchial epithelial cells, while miR-152-3p has been reported to suppress KLF5 in RAW264.7 macrophages, B cells and cervical cancer cells." (PMID 35445708, 2022). "Together with the stem cell marker KLF5, TNFRSF11A induces cancer cell proliferation, migration and invasiveness in cervical cancer." (PMID 36230614, 2022). "Some hotspot genes (e.g., KLF5, LRP1B, and KLF12) have previously been described in cervical cancer, and others (e.g., CADM2, CEP19, CSMD1, and NRROS) are reported for the first time in the present study." (PMID 34885212, 2021). "In HPV-positive cervical cancer, viral genome integrations occur on all chromosomes, with no detectable hot spots, except for the KLF5/KLF12 gene and adjacent to the MYC gene locus." (PMID 31766658, 2019).
hepatocellular carcinoma (13 papers, 2017 to 2025). A malignant tumor that arises from hepatocytes. "MiR-145-5p reduces the proliferative and migratory rates of hepatocellular carcinoma cells by targeting KLF5." (PMID 39039505, 2024). "This miRNA has been linked to proliferation, migration, and invasion of hepatoma cells through direct interaction with PTEN, a tumor suppressor, and kruppel like factor 5 (KLF5)." (PMID 34069740, 2021). "This is in accordance with a previous report that revealed the role of KLF5 in maintaining stemness properties in hepatocellular carcinoma." (PMID 33430300, 2021). "In concordance with a previous study in hepatocellular carcinoma, we found that KLF5 inhibition dramatically decreased the spheroid growth and downregulated the expression of stem cell markers such as CD44, CD133, NANOG and OCT4 in EOC cells." (PMID 33424607, 2020). "Moreover, miR-21 promotes cell migration and invasion of hepatocellular carcinoma by targeting Kruppel Like Factor 5 (KLF5)." (PMID 32083086, 2020).
melanoma (12 papers, 2014 to 2025). A malignant, usually aggressive tumor composed of atypical, neoplastic melanocytes. "Subsequent investigations showed that WWP1 overexpression in melanoma cells could mediate K48-linked ubiquitination of KLF5 and induce its proteasomal degradation, whereas BAP1 overexpression reverted this modification and increased KLF5 protein expression." (PMID 36918822, 2023). "WWP1 targets KLF5 for degradation via K48-linked ubiquitination in melanoma cells." (PMID 34226507, 2021). "KLF5 promotes malignant phenotype of melanoma cells and inhibits autophagy, leading to poor prognosis." (PMID 39835132, 2024). "An examination of the expression profiles of melanoma patients from the TCGA database, compared to normal controls from the GTEx database, revealed that AHR, MAP2K1, and PRKACB were upregulated in melanoma, whereas KLF5 and PIK3R2 were downregulated." (PMID 39835132, 2024). "BAP1 counteracts WWP1-mediated KLF5 ubiquitination, promoting melanoma development by stabilizing KLF5 within the BAP1/HCF-1 complex." (PMID 39949609, 2024). "In melanoma patients, the expression level of WWP1 was positively associated with good prognosis whereas the expression levels of KLF5 and BAP1 were found to be positively associated with poor prognosis." (PMID 36918822, 2023). "In melanoma, WWP1 mediates the K48-linked ubiquitination and degradation of KLF5, a process antagonized by oncogenic deubiquitinase BAP1." (PMID 38129384, 2023). "BAP1 blocked WWP1-induced degradation of KLF5 and led to upregulation of KLF5 and promoting melanoma development." (PMID 34226507, 2021). "KLF5 enhanced malignant phenotypes and suppressed autophagy of melanoma cells via activation of PI3K–AKT–mTOR pathways." (PMID 34226507, 2021). "Studies have shown that WWP1 is underexpressed in melanoma, where KLF5 levels are elevated." (PMID 39949609, 2024). "This study provides an integrated approach to understanding the AhR pathway’s role in melanoma, identifying MAP2K1, PRKACB, KLF5, and PIK3R2 as critical prognostic markers and therapeutic targets." (PMID 39835132, 2024). "KLF5 can promote the epithelial-mesenchymal transition (EMT), a process crucial for melanoma invasion and metastasis, making it a potential target for therapeutic interventions aimed at disrupting these pathways." (PMID 39835132, 2024). "These analyses aim to uncover potential therapeutic strategies for melanoma by targeting key molecules in the AHR, MAP2K1, KLF5, PRKACB, and PIK3R2 signaling pathways." (PMID 39835132, 2024). "This study presents a comprehensive analysis of AhR-related genes in melanoma, highlighting MAP2K1, PRKACB, KLF5, and PIK3R2 as key prognostic markers and potential therapeutic targets." (PMID 39835132, 2024). "Our analysis identified a robust prognostic model, with four AhR-related genes (MAP2K1, PRKACB, KLF5, and PIK3R2) emerging as key contributors to melanoma progression." (PMID 39835132, 2024). "These analyses aim to identify therapeutic strategies for melanoma by targeting key genes (AHR, MAP2K1, KLF5, PRKACB, PIK3R2) and their regulatory RNA networks, offering potential for personalized treatments and novel biomarkers to improve clinical outcomes." (PMID 39835132, 2024). "Studies on various melanoma cell lines (CRL-2208, HTB-65, ACC236) reveal low WWP1 expression alongside high KLF5 levels, which correlate with poor prognosis." (PMID 39949609, 2024). "The upregulation of AHR, MAP2K1, and PRKACB, alongside the downregulation of KLF5 and PIK3R2, suggests that these genes play critical roles in melanoma progression through various signaling pathways." (PMID 39835132, 2024). "Studies indicate that KLF5 can enhance the expression of CYP1A1, which are involved in inducing the expression of proinflammatory cytokines (such as TNF) that can influence melanoma progression." (PMID 39835132, 2024).
melanoma (continued). "Given that KLF4 enhanced melanoma adaptation to ER stress, we first knocked down KLF4,KLF5 and KLF8 expression using shRNAs in Mel-RM and A375 cells." (PMID 30055641, 2018). "Conversely, the downregulation of KLF5 and PIK3R2 may facilitate a more aggressive, proliferative melanoma phenotype by affecting cell differentiation and metabolism." (PMID 39835132, 2024). "Ubiquitin-mediated degradation of oncoprotein KLF5 by WWP1 could induce autophagy signaling, thereby inhibiting melanoma cell malignant phenotypes in vitro as well as progression and metastasis of melanoma in vivo." (PMID 36918822, 2023). "Notably, overexpressed KLF5 could suppress melanoma cell autophagy by activating the PI3K-AKT-mTOR pathway, thereby inducing melanoma cell malignant phenotypes in vitro as well as progression and metastasis of melanoma in vivo." (PMID 36918822, 2023). "Jia and colleagues found that BAP1 promotes melanoma migration and invasion by antagonizing WWP1-mediated KLF5 ubiquitination and degradation, suggesting that WWP1 plays a negative role in regulating invasion and migration in melanoma." (PMID 38129384, 2023).
Obesity (12 papers, 2016 to 2025). Accumulation of substantial excess body fat. "Cardiomyocyte-specific KLF5 knockout mice were found to have accelerated diet-induced obesity associated with increased white adipose tissue." (PMID 37174466, 2023). "Obesity and diabetes are the major risk factors for the development of kidney diseases and KLF5 activation is modulated in obesity and in diabetes." (PMID 33523554, 2021). "The KLF5+/− mice were afforded protection from high‐fat‐induced obesity, hypercholesterolaemia and glucose intolerance." (PMID 33523554, 2021). "Resveratrol ameliorates obesity and dyslipidemia via increasing KLF5 phosphorylation and interfering with the interaction between KLF5 and c-Myc, which subsequently modulates lipid metabolism balance." (PMID 33493334, 2021). "For example, KLF5 knockout mice are protected against high-fat diet-induced obesity, with impaired adipogenesis in mouse embryonic fibroblasts (MEFs) of KLF5+/− mice." (PMID 34065474, 2021). "Among these genes, only Egr1 and Klf5 expression and motif enrichment were enhanced by exercise, though obesity had a blunting effect." (PMID 29044196, 2017). "Moreover, expression of Cpt1b and Ucp2 in skeletal muscle is up-regulated in the klf5-knockout heterozygous mouse, which is resistant to high fat-induced obesity and glucose intolerance." (PMID 33639916, 2021). "Additionally, KLF5 heterozygous mice are resistant to high-fat diet-induced obesity." (PMID 29180716, 2017).
breast tumors (11 papers, 2015 to 2025). "In the present study, KLF5 deficiency impeded breast tumor growth by increasing the infiltration and functionality of antineoplastic T cells." (PMID 36923542, 2023). "Kruppel-like transcription factors (KLFs), which play a key role in maintaining pluripotency, and KLF4/KLF5 have been shown to be elevated in aggressive primary breast tumors, promoting metabolic reprogramming and tumor progression." (PMID 40616161, 2025). "Nevertheless, our results suggest that BAP1 promotes breast tumour growth and metastasis partially through stabilizing KLF5." (PMID 26419610, 2015). "Finally, BAP1 promotes breast tumour growth and metastasis partially through KLF5, because KLF5 overexpression partially rescued the BAP1 knockdown-induced tumour growth and metastasis inhibition." (PMID 26419610, 2015). "A significant association was observed considering the expression levels of Kruppel Like Factor 5 (KLF5) and Retinitis Pigmentosa 1 (RP1) in breast tumor cells." (PMID 36597150, 2023). "Across 890 breast tumors, the transcript abundance for KLF4, KLF5 and MCL1 was positively correlated." (PMID 25789974, 2015). "Since ATXN3L regulates KLF5 at the protein level, it will be significant to develop a good anti-ATXN3L Ab to examine the ATXN3L protein expression in breast tumors in order to assess the clinical relevance of ATXN3L." (PMID 26079537, 2015). "We also analyzed a small cohort of primary breast tumor tissues for TTK and KLF5 expression." (PMID 30206215, 2018).
diabetic nephropathy (11 papers, 2019 to 2025). "Increased KLF5 expression was also observed in diabetic kidney and diabetic kidney disease is associated with morphological changes including expansion of mesangial matrix and tubular interstitial space, as well as podocyte damage and glomerular basement membrane thickening." (PMID 33523554, 2021). "High lactate levels can accelerate the progression of diabetic nephropathy by promoting Kruppel-like factor 5 (KLF5) expression through histone lactylation, thereby facilitating EMT." (PMID 40584617, 2025). "KLF5 was found to be upregulated in renal tissues of mice with diabetic nephropathy (DN), and inhibited KLF5 could relieve podocyte injury, which may be helpful for establishing a novel DN therapy." (PMID 37506140, 2023). "Therefore, in the presence of TGF‐β, the effect of KLF5 on renal cell proliferation needs to be further studied in the context of diabetic kidney disease." (PMID 33523554, 2021). "In conclusion, these data suggest that LPA contributes to the pathogenesis of diabetic nephropathy by inducing EMT and renal tubular fibrosis via regulation of KLF5 through the LPAR1." (PMID 36142408, 2022). "And transcription factors HIF1α, KLF4, KLF5, RUNX1, SP1, VDR, WT1 may be also related to diabetic nephropathy." (PMID 34735495, 2021). "Transcription factors HIF1α, KLF4, KLF5, RUNX1, SP1, VDR and WT1 may be related to diabetic nephropathy." (PMID 34735495, 2021).
esophageal squamous cell carcinoma (10 papers, 2014 to 2025). Esophageal squamous cell carcinoma (ESCC) is a type of esophageal carcinoma (EC) that can affect any part of the esophagus, but is usually located in the upper or middle third. "Krüpple-like factor 5 (KLF5) is a zinc-finger-containing transcription factor implicated in several human malignancies, but its potential regulatory mechanisms implicated in esophageal squamous cell carcinoma (ESCC) remain elusive." (PMID 38087142, 2023). "Previous research demonstrates the interaction between SOX2 and KLF5 in the progression from normal tissue to esophageal squamous cell cancer (ESCC), suggesting a potential role in response to tissue injury." (PMID 37672481, 2023). "KLF5 expression was considerably downregulated in esophageal squamous-cell carcinoma compared to normal esophageal epithelial cells, and restoring KLF5 expression activated the JNK pathway, leading to apoptosis and decreased cancer cell survival." (PMID 35345512, 2022). "Our study indicated that KLF5 could promote esophageal squamous cell cancer proliferation, migration, and invasion by upregulating FGF-BP1/SNAIL2 signaling." (PMID 38087142, 2023). "For example, the SEs of TP63, a lineage-specific master TF, are co-occupied with other CRC TFs (SOX2, KLF5, and TP63), and three SE constituents are required to transcribe TP63 as well as induce esophageal squamous cell carcinoma (ESCC) progression." (PMID 37501079, 2023).
glioblastoma (10 papers, 2019 to 2025). The most malignant astrocytic tumor (WHO grade IV). "MCM3AP-AS1 is also upregulated in glioblastoma and regulates angiogenesis through the miR-211/KLF5/AGGF1 axis." (PMID 34256796, 2021). "In addition, KLF5 boosts glioblastoma angiogenesis via enhancing the promoter activity of angiogenic factor with G-patch and FHA domain 1 (AGGF1), which is identified as a pro-angiogenic factor and associated with angiogenesis in various cancers." (PMID 33493334, 2021). "MCM3AP-AS1 induces angiogenesis in glioblastoma by regulating the miR-211/KLF5/AGGF1 axis." (PMID 34271873, 2021). "Evaluation of three independent glioblastoma (GBM) cohorts (CGGA, E_TABM, GSE74187) demonstrated that elevated KLF5 expression was significantly linked to poorer OS and PFS in patients." (PMID 41583492, 2025). "In glioblastoma multiforme, MCM3AP-AS1 is also upregulated and interacts with the miR-211/KLF5/AGGF1 axis to promote tumor angiogenesis." (PMID 34271873, 2021). "Knockdown of KLF5 also represses PI3K, AKT, and ERK1/2 activities, together with AGGF1, contributing to suppressed angiogenesis in glioblastoma." (PMID 33493334, 2021).